MTOR (mechanistic target of rapamycin kinase)
Diseases named in the same sentence as MTOR in open-access papers (continued):
Sharing a sentence is not in itself a finding about the gene and the disease.
diabetes (continued). "A further alternative strategy to circumvent high dose rapalogue-induced glucose intolerance is to use mTOR inhibitors in combination with anti-diabetes medicines, such as metformin—another promising longevity therapeutic in its own right." (PMID 30096787, 2018). "In contrast, a suppression of the PI3K/Akt/mTOR pathways and an impairment in satellite cell activation and proliferation appear to occur during the course of diabetes." (PMID 30510624, 2018). "In the present study, we studied the expression of Foxo1, Gsk3β and PI3K-Akt-mTOR in the brain of streptozotocin-induced type 2 diabetes mellitus Wistar rats." (PMID 30041644, 2018). "mTOR signal transduction is abnormal in many diseases, such as cancer, cardiovascular disease, and diabetes, and many experiments have shown that PI3K/Akt/mTOR signaling pathway is directly related to cardiac injury and cardiomyocyte apoptosis." (PMID 30405071, 2018). "We propose a scenario for the development of permanent neonatal diabetes, possibly also common forms of diabetes, where early-life events inducing ER stress affect β-cell mass expansion due to mTOR inhibition." (PMID 30412050, 2018). "Since PP2A activity is involved in diabetes, the PP2A-KI mice will be a useful model with which to study the effect of diabetes on mTOR activity in PP2A-KI mice." (PMID 29416710, 2018). "Among the most common undesirable effects of mTOR inhibitor therapy is metabolic syndrome that implies hyperglycemia with de novo diabetes mellitus (DM) and dyslipidemia." (PMID 30034573, 2018). "Under pathological glucose conditions, aberrant O-GlcNAcylation levels result in activation or inhibition PI3K/AKT/mTOR signaling pathway as found in cancer and diabetes, respectively." (PMID 30356686, 2018). "When the formation of mTOR signaling and complex formation is disturbed, the effects contribute to common pathobiologies found in cancer and diabetes including cell stress, apoptosis, metabolic shifts, protein sysnthesis dysregulation, and insulin signaling." (PMID 29529022, 2018). "One of the evidence for connecting diabetes and AD is the signaling factor mammalian target of rapamycin (mTOR)." (PMID 29802157, 2018). "Inhibition of mTOR (mammalian target of rapamycin) slows aging and postpones age-related diseases like diabetes, cancer and cardiovascular diseases and widely accepted aging model by activating autophagy." (PMID 29050357, 2017). "The Akt/mTOR pathway is the central regulator of metabolism that plays a pivotal role in the pathogenesis of diabetes." (PMID 29225596, 2017). "In global diabetes‐related ce‐network, we focused on mTOR subnetwork due to the central role of mTOR in energy metabolism." (PMID 28643459, 2017). "Metabolic disorders such as diabetes and obesity are marked by alterations in the principal nutrient-sensing mechanisms AMPK and mTOR and are associated with an increased risk of cardiovascular diseases and stroke." (PMID 28690762, 2017). "Oxidative stress and mTOR signaling crucially regulate cardiometabolism, affecting MI/R injury under diabetes." (PMID 28298952, 2017). "Taken together, these results support a pathway in which reduced IGF-1 in diabetes leads to suppressed activation of the mTOR pathway, which further reduces IGF-1." (PMID 28729536, 2017). "A second clinical trial, conducted by Diabetes TrialNet and the Immune Tolerance Network, used higher doses of IL-2 in combination with the inhibitor of the mammalian target of rapamycin (mTOR), rapamycin." (PMID 28770318, 2017). "The pathological roles of PTEN, mTOR, and Akt have been well established in different diseases including diabetes and different types of cancer." (PMID 28659828, 2017). "Metformin, a commonly utilized diabetes medication has properties as an mTOR inhibitor and has been investigated with underwhelming results mostly in a retrospective fashion." (PMID 28423681, 2017).
diabetes (continued). "NAC treatment prevented diabetes and I/R induced increases in mTOR (p < 0.05, D4w + I/R + NAC versus D4w + I/R)." (PMID 28265179, 2017). "We further validated two ceRNA pairs (MALAT1‐miR‐144‐mTOR and NEAT1‐miR‐181b‐mTOR) involved in mTOR pathway and explored their significance in diabetes mellitus." (PMID 28643459, 2017). "Ang II treatment also augmented diabetes-associated increased phosphorylated levels of c-Jun, JNK, mTOR, and miR-221, and decreased of p27 expression, a direct target of miR-221." (PMID 29290979, 2017). "The interaction of aging and metabolic pathways, including p66SHC, SIRT1, or AMPK/mTOR/S6K, with telomere erosion in the presence of diabetes or obesity is a promising field to reveal how metabolic disorders impact on aging." (PMID 26968134, 2016). "Activation of mTOR is also reported in other pathological conditions, such as aging, obesity, insulin resistance, and diabetes, where mTOR inhibition seems to be beneficial." (PMID 27462398, 2016). "Blood glucose level monitoring is recommended in patients receiving treatment with mTOR inhibitors because mTOR inhibitors are accompanied by a high incidence of hyperglycemia and new-onset diabetes (13%–50%) when used as anticancer drugs." (PMID 27338360, 2016). "We evaluated directly the effect of maternal diabetes on embryonic mTORC1 signalling using antibodies to detect relative pools of phosphorylated and total mTOR." (PMID 26020623, 2015). "Deregulation of the mTOR signaling pathway plays a central role in the transformation and the uncontrolled growth of numerous cancers, as well as roles in diabetes, obesity, neurodegeneration, and aging." (PMID 26473364, 2015). "As a key sensor of cellular energy/nutrient abundance and stress, the mTOR signaling pathway is critically involved in the onset and progression of diabetes, cancer and aging." (PMID 26042770, 2015). "In in vivo experiments, dual inhibition of PI3K and mTOR resulted in a reduction of proliferation of rat diabetes related CCT and increased autophagic activity." (PMID 25948777, 2015). "Chronic comorbidities such as diabetes are known to interfere with conditioning interventions by modulating cardioprotective signaling pathways, such as e.g., mTOR pathway and autophagy." (PMID 26581389, 2015). "A signalling pathway crucial to the onset/progression of cancer and diabetes is the phosphatidylinositol-3-kinase (PI3K)/AKT/mammalian target of rapamycin (mTOR) pathway." (PMID 25866760, 2015). "Because mTOR signaling regulates several aspects of metabolism, the potential of leucine as a dietary supplement for treating obesity and diabetes mellitus has been investigated." (PMID 26007339, 2015). "The induction of diabetes increased tuberin phosphorylation/inactivation and resulted in the activation of mTOR as evidenced by the increase phosphorylation of its downstream target p70S6K at Thr389." (PMID 24797175, 2014). "Dysregulation of mTOR signaling induces various disorders including cancer, diabetes, obesity, cardiovascular disease, inflammation, and neurodevelopmental and neurodegenerative disorders." (PMID 24795562, 2014). "Given the involvement of the mTOR pathway in pathophysiology of cancer, diabetes and aging, regulation of mTOR activity is extensively studied; however, up to date, the majority of work has been done in cell culture." (PMID 25239872, 2014). "Our data were also supported by Xu’s study, in which diabetes activates Akt and mTOR while inhibites AMPK signaling in the heart." (PMID 24466263, 2014). "Although mTOR is an important regulator of neuronal development and function, including tau expression, to date only few studies have addressed a possible implication of mTOR in diabetes in relation to protein aggregate formation in brain tissue." (PMID 24393531, 2014).
diabetes (continued). "The ribosomal P70 S6 kinases play a crucial role in PI3K/mTOR regulated signalling pathways and are therefore potential targets for the treatment of a variety of diseases including diabetes and cancer." (PMID 24072592, 2013). "This review will focus on the regulation of intimal hyperplasia and potential changes in the role of the mTOR pathway in intimal hyperplasia in the presence of diabetes." (PMID 24276258, 2013). "Mutation in the gene encoding Mtor in mice is embryonically lethal, whereas increased activity of mTOR induces metabolic dysfunctions including obesity and diabetes." (PMID 22851226, 2013). "Several drugs already in clinical use target the AMPK or mTOR kinases to treat diseases such as cancer and diabetes." (PMID 24098109, 2013). "Yet, mTOR can, at times, alter insulin signaling and lead to insulin resistance in the cardiovascular system during diabetes mellitus." (PMID 22545721, 2012). "Similar to mTOR and 4E-BP1, the protein degradation-associated genes MuRF-1 and MAF-bx were altered by the induction of diabetes, demonstrating significant increases at the protein or mRNA levels, or both." (PMID 23239980, 2012). "It is therefore vital to understand the complex relationship mTOR and its downstream pathways hold during metabolic disease in order to develop novel strategies for the complications of diabetes mellitus in the cardiovascular system." (PMID 22545721, 2012). "The acquisition of such knowledge is critical for designing effective therapeutic strategies for treatment and cure of diabetes as well as to understand the effects of mTOR inhibitors in β-cell function." (PMID 24893199, 2012). "The acquisition of such knowledge is critical for the design of improved therapeutic strategies for the treatment and cure of diabetes as well as to understand the effects of mTOR inhibitors in β-cell function." (PMID 24893199, 2012). "In diabetes induced by streptozotocin sirolimus treatment produced a reduction of albuminuria and the expression of renal mTOR and TGFβ." (PMID 22427849, 2012). "From this, new research directions are emerging with regard to the role of AKT/mTOR in diabetes and T cell-mediated immunity." (PMID 22680924, 2012). "Given these concerns, the signaling pathways of the mammalian target of rapamycin (mTOR) offer exciting prospects for the development of novel therapies for the cardiovascular complications of diabetes." (PMID 22545721, 2012). "Aberrant activation of mTOR and S6K has been shown to play a critical role in the development of diabetes and diabetic nephropathy." (PMID 21818401, 2011). "Additional studies have shown that the commonly-prescribed diabetes drug Metformin will also inhibit mTOR and prevent cellular aging." (PMID 21422497, 2011). "High caloric intake increases mTOR activity and can contribute to insulin-resistance, diabetes, obesity and augment cancer growth and premature aging." (PMID 21487160, 2011). "By conducting these analyses independently of Metacore, we confirmed the relationship between the mTOR pathway and some human diseases, such as multiple sclerosis, diabetes, arthritis and some cancers." (PMID 18980674, 2008). "Abnormal catabolism of BCAA participates in the pathogenesis of various diseases such as diabetes, cardiovascular diseases, and cancer by affecting the mammalian target of mammalian target of rapamycin (mTOR) pathway, mitochondrial function, and epigenetic modifications." (PMID 41503231, 2026). "After the onset of diabetes, the levels of human autoinflammatory factors and reactive oxygen species increase, which can activate RTKs and GPCRs, leading to the phosphorylation of mTOR to activate mTOR." (PMID 40046742, 2025). "For example, diabetes seems to directly hinder the effects of mammalian target of rapamycin (mTOR) inhibition on vascular smooth muscle cell (VSMC) proliferation, mandating at least a tenfold higher drug concentration in order to achieve a similar level of inhibition." (PMID 41212864, 2025).
diabetes (continued). "Drugs or exercises targeting the mTOR may yield treatment strategies for the chronic diseases such as diabetes and sarcopenia." (PMID 40950953, 2025). "mTOR is considered a target in many diseases such as Alzheimer's disease, diabetes, and cancer." (PMID 41473273, 2025). "The activation of the mTOR pathway can trigger a series of signaling cascades such as the release of inflammatory cytokines, oxidative stress, apoptosis and autophagy, which will further aggravate the progression of diabetes." (PMID 40046742, 2025). "The mTOR pathway regulates critical cellular processes, exhibiting dual roles in diabetes by both promoting β-cell proliferation (compensating for insulin resistance) and contributing to tissue damage (e.g., kidney dysfunction and metabolic immune dysregulation)." (PMID 41009376, 2025). "Metformin and Rapamycin are both common drugs used for the treatment of diabetes; however recent data indicates that they may possess longevity benefits by suppressing the mTOR pathway." (PMID 38533302, 2024). "mTOR activation may enhance β-cell proliferation and insulin secretion with subsequent reduction in glycemia, thus protecting against diabetes." (PMID 39201476, 2024). "Several studies have unveiled the role of mTOR in β-cell function and glucose homeostasis since embryogenesis; however, to date, it remains inconclusive whether the mTOR pathway positively or negatively impacts diabetes pathogenesis." (PMID 39201476, 2024). "This elevation in IGFBP2 with TRE, potentially impacting the AKT/mTOR pathway, may have implications for cardiovascular disease, diabetes, cancer, and aging." (PMID 39458471, 2024). "Inthe diabetic disease state where insulin signaling is impaired, control of GLUT1expression by mTOR signaling shown here may connect impaired phagocyte GLUT1expression to worse S. aureus infection outcomes in diabetes." (PMID 38767353, 2024). "In this case- control study, mTOR was able to identify microvascular complications in T2DM patients with excellent diagnostic performance, suggesting that mTOR is a promising predictor of diabetes-related microvascular complications in patients with T2DM." (PMID 39261960, 2024). "Furthermore, an exaggerated mTOR pathway in diabetes inhibits BDNF signaling leading to neuroinflammation and synaptic dysfunction in diabetic encephalopathy." (PMID 38006577, 2024). "Accordingly, there is accumulating evidence that the beneficial effects of various compounds on the diabetes-induced cognitive deficits are due to a re-established activation of the PI3K/Akt/mTOR pathway and reduced oxidative stress, neuroinflammation, and autophagy." (PMID 38137892, 2023). "The dysregulation of mTOR is involved in the progression of both cancer and diabetes." (PMID 36927703, 2023). "A tightly balanced mTOR activity is essential to maintain normal renal function in diabetes." (PMID 37920252, 2023). "Since diabetes is a systemic disease impacting numerous metabolic pathways, including mTOR signaling, we hypothesized that targeting the 5-HT6-mTOR pathway may have considerable effects on painful diabetic neuropathy." (PMID 36830733, 2023). "It has been suggested that anti-adipogenic activities of polyphenols are applied through the mechanistic target of rapamycin (mTOR) signaling pathway that is involved in the pathogenesis of numerous other comorbidities including diabetes, metabolic syndrome and CVD." (PMID 38012598, 2023). "Decreased control of AMPK over mTOR leads to increased mTOR activity, which may eventually lead to several age-related diseases, including diabetes and OA." (PMID 36879307, 2023). "In addition, the mTOR signaling pathway can influence the activity of immune cells related to lipid metabolism, and the development of metabolic diseases, such as diabetes and obesity." (PMID 37959108, 2023). "Hence, mTOR seems to positively regulate inflammatory responses in bone tissue and aggravate diabetes-induced bone metabolic aberrations." (PMID 37298150, 2023).
diabetes (continued). "However, it is worth noting that though overactivation of mTORC1 in diabetes aggravates kidney lesions, mTOR activity is necessary to maintain podocyte homeostasis." (PMID 37920252, 2023). "mTOR controls, at least in part, four major metabolic processes responsible for the regulation and maintenance of normal levels of hepatic triglycerides (TG) amounts, which are altered in individuals with insulin resistance, obesity, and diabetes mellitus." (PMID 37760534, 2023). "A recent study showed that isorhamnetin decreased the expression of mTOR which might be also another mechanism by which isorhamnetin improves insulin sensitivity which needs to be studied in such a model of diabetes." (PMID 36677559, 2023). "Furthermore, a recent study reported that mTOR was differentially involved in tubular autophagy activity via the insulin/mTOR pathway in the presence of nephropathy, depending on the type of diabetes." (PMID 36299884, 2022). "A third hypothesis could be that in other indications (malignancies), mTOR inhibitors are combined with other antineoplastic agents that can increase the incidence of diabetes (for instance steroids)." (PMID 35804402, 2022). "The mTOR/PI3K/Akt pathway was involved in the regulation of autophagy in diabetic kidney." (PMID 35449001, 2022). "The notable canonical pathways shared between both CUR groups in the different dietary regimens included insulin secretion and insulin receptor signaling pathways, the senescence pathway, IGF-1, mTOR, and Hif1 α signaling, and Type 2 diabetes mellitus signaling." (PMID 35017319, 2022). "Since PI3K signaling through mammalian target of rapamycin (mTOR) is involved in fibrotic processes of the heart, we aim at further functional investigation of this particular Akt-downstream signaling pathway in the context of diabetes-induced CAVD." (PMID 36386326, 2022). "The PI3K/AKT/mTOR pathway has been shown to play a key role in allergic diseases and diabetes." (PMID 36496564, 2022). "In addition, continuous hyperactivation of MTOR in diabetic myocardium has been demonstrated, which makes MTOR become a potential target in the prevention of diabetes-related cardiovascular disease." (PMID 36532549, 2022). "Given the central role of mTOR in senescence and inflammation, it will be extremely interesting to assess the clinical effects of mTOR inhibition on age-related bone fragility and in patients with diabetes." (PMID 35388291, 2022). "Research evidence has demonstrated that dysregulation of the mechanistic target of rapamycin (mTOR) signaling axis is involved in disease onset covering a broad spectrum of conditions from diabetes to various tumor types as well as inflammatory skin disorders and skin cancers." (PMID 35163615, 2022). "Moreover, a recent study using a mouse model reported that mTOR was differentially involved in tubular autophagy activity via the insulin/mTOR pathway in the presence of nephropathy, depending on the type of diabetes." (PMID 36299884, 2022). "Impaired mTOR signaling is involved in diabetes and cardiovascular events." (PMID 35216514, 2022). "More importantly, key genes of the respective pathways, such as AKT3, FGF2, FGF7, mitogen-activated protein kinase 4 (MAP3K4), MAP3K5, insulin receptor (INSR), AKT3, and mTOR, were also enriched in the analysis, thus explaining the link between diabetes and BCRL subjects in the present study." (PMID 36232660, 2022). "Consistent with the change trends of mTOR and autophagy in our study, the p‐tau and Aβ levels roughly returned to normal in surgery‐treated rats by postoperative day 14 but remained elevated in surgery‐treated rats with diabetes." (PMID 34784444, 2022).